EZH2 (enhancer of zeste 2 polycomb repressive complex 2 subunit)
Diseases named in the same sentence as EZH2 in open-access papers (continued):
Sharing a sentence is not in itself a finding about the gene and the disease.
tumor (continued). "In addition, in vivo, the subcutaneous tumor formation rate in mice implanted with EZH2 knockout clones was obviously reduced (from 100 to 0%) compared to that in mice implanted with wild-type SKOV3 cells (p = 0.0021)." (PMID 33163485, 2020). "Previous studies have reported that EZH2 plays an essential role in anti-tumor immunity." (PMID 33180829, 2020). "PVT1 functions as a tumor promoter in NSCLC via sequestering miR-526b to modulate EZH2." (PMID 33088221, 2020). "Previous studies have shown that the disruption of EZH2 in regulatory T cells (Tregs) can enhance anti-tumor immunity by diminishing the suppressive activity of Tregs and enhancing T cell infiltration in the tumor." (PMID 33180829, 2020). "Four tumours had a higher degree of nuclear pleomorphism than seen in the MPNST classical variant (HP Group 2), three of which (cases 19, 34, and 37) harboured LOH in EZH2." (PMID 32666581, 2020). "Many arguments link EZH2 expression to tumor immunogenicity, suggesting that interfering with EZH2 expression could modulate the response to ICIs." (PMID 32708698, 2020). "In mice, TNF can promote EZH2 expression in tumor cells and trigger tumor recurrence." (PMID 32000802, 2020). "HNF1B is a transcription factor with tumor suppressive function, and our data indicate that it might be suppressed by the EZH2-mediated histone H3K27me3 pathway, in addition to previously reported DNA methylation." (PMID 31636385, 2020). "EZH2 inhibitors have been reported to sensitize many types of tumor cells to antitumor drugs." (PMID 33276757, 2020). "EZH2 targets various tumor suppressor genes to promote cancer progression, including PTEN." (PMID 32242003, 2020). "Indeed, our current study showed that UPK1A-AS1 plays an oncogenic role by modulating EZH2 activity because the downregulation of EZH2 abrogated the tumor-promoting activity of UPK1A-AS1 in HCC." (PMID 33121524, 2020). "Inhibition of EZH2 leads to reduced tumor formation and growth." (PMID 33230143, 2020). "In the HNSCC model of Anti-PD-1 resistance, combination therapy with Anti-PD-1 and EZH2 inhibitor could inhibit tumor growth." (PMID 33344447, 2020). "We tested this for all HDACs and EZH2 in our set of 64 tumours." (PMID 33316946, 2020). "Although this enzyme represses CIITA transcription by the K27m3 of histone 3, thereby silencing HLA Class II expression, we observed a high expression of EZH2 in high-risk M3 tumours, without any association to HLA Class I expression." (PMID 33316946, 2020). "Additionally, higher expression of EZH2 mRNA was confirmed in HNSCC patients and is correlated with overexpression of DNMT3A, as well as with stage of cancer and recurrence, which suggests a role of EZH2 in tumor progression." (PMID 31712935, 2020). "Similarly, our study also found that EZH2 is overexpressed in BC and is correlated with the size of tumours, lymph node metastasis and poor prognosis of TNBC patients." (PMID 32725802, 2020). "It was reported that CRNDE bound with EZH2 to facilitate tumor progression in colorectal cancer." (PMID 32826865, 2020). "EZH2 silences the tumor suppressor genes with its histone methyltransferase." (PMID 32641029, 2020). "Next, we investigated in vivo whether silencing of EZH2 could retard the growth of tumor xenografts in nude mice." (PMID 33292225, 2020). "EZH2 present in the cytoplasm may participate in actin polymerization to influence tumor dissemination." (PMID 33121524, 2020). "We have then tested whether EZH2 inhibitor (DZNep) induces apoptosis and/or cell death in tumor spheroid." (PMID 31996670, 2020). "Finally, xenograft tumour models were used to demonstrate that curcumin restored DLC1 expression by inhibiting EZH2 and also inhibited the growth and promoted the apoptosis of TNBC cells." (PMID 32725802, 2020).
tumor (continued). "Based on our findings, it is possible that co-administration of inhibitors of MEK, PI3K, mTOR, IDH1, EZH2 or CDK4/6 (to target CDKN2A deletion) may have been effective in slowing or reducing tumour progression." (PMID 33053751, 2020). "We focused on some important events, for example, pathways of oncogenesis by Met, EIF4 pathway, downregulation of SMAD2-SMAD3-SMAD4 transcriptional activity, EZH2 targets, stemness, well vs. poorly differentiated tumor, epithelial mesenchymal transition, UV response via ERCC3, and metastasis." (PMID 32754191, 2020). "EZH2 is highly expressed in various tumors, such as breast cancer, prostate cancer, endometrial cancer and melanoma, where it often correlates with advanced tumor stages and poor prognosis." (PMID 33230143, 2020). "Of note, the regulation of PIK3IP1 is dependent on EZH2 methyltransferase and inhibition of EZH2 activity combined with loss of ARID1A expression is synthetically lethal, highlighting a potential therapeutic vulnerability through the use of EZH2 inhibitors in this tumour." (PMID 33053751, 2020). "We found silencing the expression of EZH2, glucose uptake and lactate production of PC cells were significantly reduced, suggesting that EZH2 could inhibit the glycolysis of tumor cells." (PMID 33072570, 2020). "These tumor suppressor miRNAs are directly repressed by EZH2 in HMCLs and tumor PC." (PMID 33126754, 2020). "EZH2 can promote the proliferation and spread of tumor cells through inhibiting the characteristic target genes in chromatin, and the mechanism of its transcriptional inhibition may be related to its regulatory effect on histone methyltransferase." (PMID 31966062, 2020). "MiRNA has been reported to function as a tumor suppressor in various cancers by targeting multiple oncogenes, including EZH2, and it can inhibit the expression of mRNA by binding to the 3’UTR region of the downstream target gene to suppress translation or degrade mRNA." (PMID 33718109, 2020). "EZH2 overexpression has been reported in multiple tumor types." (PMID 33276757, 2020). "Therefore, the comination of EZH2 inhibitor with anti-HER2 can elicit the anti-tumor effect through modulating both the tumor instrinic and immune microenvironment mechanisms." (PMID 33208750, 2020). "We hypothesize that this conversion is not due simply to statistical unevenness but may be the result of different biological effects, which occur after a critical EZH2 activity is reached in the concerned tumor cells." (PMID 33230143, 2020). "In BC, miR-92b may negatively regulate the expression of EZH2, promoting autophagy and decreasing tumor cell viability, migration, and invasion." (PMID 33014831, 2020). "Disruption of EZH2 activity in Tregs, either pharmacologically or genetically, drove the acquisition of pro-inflammatory functions in tumor-infiltrating Tregs, remodeling the tumor microenvironment and enhancing the recruitment and function of CD8+ and CD4+ effector T cells that eliminate tumors." (PMID 32723346, 2020). "In addition to EZH2 and SETD2, KMTs such as G9a, MLL, DOT1L and NSD1 are associated with tumor development and progression." (PMID 32859239, 2020). "Also, we found that in 06 cases with methylation as well as up-regulated EZH2 protein expression RUNX3 was downregulated in tumor tissue." (PMID 32943993, 2020). "Therefore, it was cleared that PAR5 exhibits its anti-tumour activity by impairing the oncogenic roles of EZH2." (PMID 33126409, 2020). "Besides, EZH2 siRNA in combination with taxanes produced more robust anti-tumor effects versus those induced by monotherapies." (PMID 32699528, 2020). "Inhibition of EZH2 could be a novel immunotherapeutic target for promoting HCC anti-tumor immunity to overcome checkpoint blockade resistance." (PMID 33180829, 2020).
tumor (continued). "EZH2 is considered to be an oncogene, but inhibition of EZH2 activity in some solid tumors does not inhibit tumor growth due to changes in H3K27 trimethylation caused by EZH2 and also causes changes in H3K27 acetylation." (PMID 31065671, 2020). "We determined whether high-risk tumours expressed the target of two drugs, histone deacetylase (HDAC) inhibitor Quisinostat and Tazemetostat, an inhibitor of Enhancer of zeste homologue 2 (EZH2)." (PMID 33316946, 2020). "Considering that PTC596 can target both BMI1 and EZH2, it is recommended that in vitro and in vivo pre-clinical studies with pHGG cell lines be undertaken first to test for possible de-differentiation toward a more aggressive tumor phenotype." (PMID 31934644, 2020). "In this study, we found that a therapeutic combination of an EZH2 inhibitor and gefitinib could significantly inhibit tumor growth and metastasis in primary gefitinib-resistant cells both in vivo and in vitro." (PMID 33276757, 2020). "Given the potency of EZH2 in strengthening stemness of CSCs and motility, we, in the present study, hypothesized that EZH2 endowed tumor cells with enhanced malignant features during liver metastasis in UM." (PMID 32127003, 2020). "Amounts of EZH2 frequently correlate with tumor growth, development, and prognosis." (PMID 33732505, 2020). "EZH2 inhibitor can also enhance the sensitivity of tumor cells to a variety of anti-tumor drugs." (PMID 31109434, 2019). "To test the effect of downregulating Ezh2 expression, rather than complete loss of function through conditional gene targeting, and to determine effects on the growth of established tumor cells, we stably silenced Ezh2 in cells from the MMTV-NIC model." (PMID 31263101, 2019). "Epigenetic therapies using EZH2 inhibitors have to be carefully evaluated for each specific tumor type, since alterations in cell differentiation might lead to unfavorable results." (PMID 31317325, 2019). "In contrast, Ezh2 acts as a tumor suppressor during AML induction." (PMID 30890554, 2019). "Many different ubiquitin E3 ligases have been reported to control Ezh2 in different tumor types." (PMID 31856907, 2019). "Loss of EZH2 at tumor invasion front, but not in tumor center was correlated with unfavorable prognosis and more advanced tumor stages." (PMID 31317325, 2019). "We next investigated whether miR‐124/506 overexpression or EZH2 inhibitor had any effect on the tumour formation in vivo." (PMID 31087496, 2019). "Importantly, EZH2 is essential for tumor formation after conditional loss of SMARCB1 in mice, and treatment with small molecule EZH2 inhibitors led to regression of RT in a xenograft model." (PMID 31123059, 2019). "EZH2 inhibition is sought to represent a good strategy for tumor therapy." (PMID 31419226, 2019). "Thus, our data reveal that the tumor-suppressive functions of Ezh2 are to maintain repression of a small number of oncogenes, including Plag1 and potentially Lin28b, which, upon derepression, contribute to more rapid AML development." (PMID 30890554, 2019). "By inhibiting the natural killer cell-mediated eradication of tumor cells, EZH2 may create an immune microenvironment that is conducive to HCC cells (Bugide, Green & Wajapeyee, 2018)." (PMID 31695969, 2019). "Based on these observations, our data suggest that EZH2 inhibition-mediated increase in NK cell activity has the potential to boost response to cisplatin therapy through increased cytotoxicity of pluripotent cells or tumor cell differentiation." (PMID 30692641, 2019). "Also the finding that a complete elimination of EZH2 is impossible in certain tumor cell lines due to gene essentiality shows that fate control by EZH2 is strongly cell type specific." (PMID 31317325, 2019). "Furthermore, EZH2 has been linked to epigenetic inactivation of WNT5A, a proposed tumor suppressor, during TGF-ß-induced epithelial-mesenchymal transition in an in vitro model of CRC." (PMID 31864341, 2019).
tumor (continued). "In particular, we were interested in the role of EZH2 in certain tumor areas." (PMID 31317325, 2019). "In contrast, the role of bivalency in tumours that overexpress EZH2 but lack activating mutations has not been established." (PMID 30926792, 2019). "The differences in EZH2 expression between tumor center and invasion front as well as different scoring and cutoff values can most likely explain controversial literature data concerning the prognostic value of EZH2." (PMID 31317325, 2019). "Taken together, these data provide reassurance that despite its tumor-suppressive effects during leukemogenesis, EZH2 may be a promising therapeutic target in established AML." (PMID 30890554, 2019). "3-DZNeP has been reported as an inhibitor of EZH2 with anti-tumor and renal protective effects." (PMID 31043583, 2019). "In addition to its role in regulating CNS development and maintenance, recent evidence suggests that EZH2 also exerts an important tumour‐suppressive function in the brain." (PMID 31468686, 2019). "In addition to repression of regular genes, YY1 has also been shown to repress tumor suppressive miR-146a in prostate cancer cells upon interacting with EZH2 and thereby promotes prostate tumor growth." (PMID 31824839, 2019). "Inhibition of methyltransferase EZH2 has shown durable tumor regression in MRT." (PMID 31835848, 2019). "Furthermore, it has been reported that inhibition of Ezh2 by DZNep was able to reduce self-renewal and tumor-initiating features of glioblastoma multiforme CSCs in vivo through the transcriptional regulation of oncogene MYC." (PMID 31320814, 2019). "For those tumours that are insensitive to EZH2 inhibition, BRM inhibition could be a promising alternative." (PMID 30898143, 2019). "Moreover, for the first time we suggest a possible link between cell cycle stop and higher aggressiveness when EZH2 is inhibited, a phenomenon that is well known for the tumor invasion front." (PMID 31317325, 2019). "While the efficacy of EZH2 inhibitors has been described in ongoing clinical trials, we provide the first insight into the mechanism of EZH2 inhibition-induced tumor cell death and show evidence of a possible resistance mechanism in an INI-1 deficient P-ES PDX." (PMID 31331120, 2019). "As a well‐known tumor suppressor, miR‐101 has multiple targets, including Fos, EZH2, Cox‐2, N‐myc, and Mcl‐1, that play roles in cancers 29, 30, 32, 33, 34, 35, indicating that the activity of miR‐101 is performed through various mechanisms by targeting different genes." (PMID 30984544, 2019). "The biological functions of EZH2 in different tumor cells are under intense investigation." (PMID 31886200, 2019). "In this study, using EZH2 as a paradigm, we set out to understand how epigenetic regulators that play essential roles in establishing and maintaining normal cell identity are repurposed by cancer cells as tumour‐promoting factors." (PMID 31468686, 2019). "Many recent studies have shown that lncRNAs could inhibit the expression levels of some factors (such as P21 and P51) that negatively regulate tumor cell proliferation by interacting with EZH2." (PMID 31016892, 2019). "ADQ specifically bound the 36G46A site in the 5′ functional domain of HOTAIR and efficiently disrupted the interaction between HOTAIR and EZH2 both in vitro and in orthotopic tumor mouse models, thereby reducing the H3K27-mediated tri-methylation of NLK and consequently inhibiting tumor metastasis." (PMID 30764859, 2019). "Indeed, treatment of the tumor cells with EZH2 specific inhibitor EPZ-6438 more significantly increased the levels of luminal markers ERα, GATA3, and CK18 in 3D cultures than in 2D culture." (PMID 31704972, 2019). "Given the important role of EZH2 in maintaining self-renewal of ESCs through silencing of differentiation programmes, we focused on investigating EZH2 as a potential driver of CC-IC self-renewal and tumour growth." (PMID 30926792, 2019).
tumor (continued). "Given the role of EZH2 in tumor immunity, we speculated that it would have a regulatory effect on PD-L1 expression in HCC." (PMID 31727135, 2019). "As recently suggested in the literature, the antitumor activity of EZH2 inhibitors could rely in part on tumor-infiltrating Treg reprogramming and consequent enhancement of anti-cancer immunity." (PMID 31331120, 2019). "Murine Ezh2+/+ MLL-AF9 spleen tumor cells cultured in vitro demonstrated sensitivity to GSK343 with an IC50 (concentration where 50% maximal growth inhibition is observed) of ∼10 μM and showed a significant reduction in colony size and formation in its presence compared with vehicle control." (PMID 30890554, 2019). "We propose that EZH2 acts as a tumour suppressor in all normal or premalignant cells, where it exerts its physiological function and cooperates with other epigenetic regulators to maintain proper cell identity in the face of cell‐extrinsic or intrinsic perturbations." (PMID 31468686, 2019). "Among them, EED226 could induce a conformational change upon its binding to EED and demonstrated sustained sustain tumor regression effects in EZH2-mutant preclinical DLBCL model." (PMID 31752930, 2019). "Finally, ablation of MELK/EZH2/NF-κB axis can impair stemness of GSCs and promote differentiation, leading to a reduced tumor burden." (PMID 31380279, 2019). "EZH2 overexpression has been found in several malignant tumor tissues, while its expression and function in PTC are largely unknown." (PMID 31718595, 2019). "Its inhibition (EZH2) may disturb cell signaling pathways that lead to tumor cell proliferation, and may simultaneously promote apoptosis in these cells." (PMID 31756998, 2019). "EZH2 both fulfills its oncogenic and tumor suppressive roles in a variety of cancers." (PMID 31921860, 2019). "However, subsequent studies suggested that Ezh2 is dispensable for breast carcinogenesis or that Ezh2 inhibition is tumor-promoting." (PMID 31263101, 2019). "However, galectin-9 overexpression exerts anti-tumor effects both in vitro and in vivo, effects that contrast with those of EZH2 but parallel with those of miR-22." (PMID 29316949, 2018). "Mechanistically, CARM1 promotes EZH2-mediated silencing of target tumor suppressor genes." (PMID 29434212, 2018). "Importantly, these new results point the attention to the complexity of the pathways directly and indirectly influenced by EZH2 to the point that this protein can function as either a tumor suppressor or promoter depending on the cellular context." (PMID 30510924, 2018). "Recent studies demonstrated that inhibition of the interaction between EZH2 with PRC2 complex may also be a specific approach with efficacy against various neoplastic diseases with decreased toxicity." (PMID 29556394, 2018). "Given the well-established role of TSP1 in blocking angiogenesis, we next investigated whether activation of beta-adrenergic signaling increases tumor angiogenesis through the CREB/EZH2/TSP1 pathway." (PMID 30287808, 2018). "Interestingly, while our approach of using in vivo transgenic models allowed us to test progression of the metastatic cascade in a biologically relevant way, it also uncovered novel insights into the role of Ezh2 in tumour onset and progression." (PMID 29959321, 2018). "EZH2 upregulation in gliomas maintains stemness of tumor cells by inhibiting their differentiation." (PMID 29642503, 2018). "Furthermore, xenograft tumor models were established to verify the effects of miR‐144‐3p on tumor formation and EZH2, VEGFA, MMP2 and MMP9 expressions in vivo." (PMID 30280514, 2018).